MDM2 (MDM2 proto-oncogene)
Diseases named in the same sentence as MDM2 in open-access papers (continued):
Sharing a sentence is not in itself a finding about the gene and the disease.
breast carcinoma (continued). "In present study, we revealed that ZLM-7 could block cell-cycle progression and therefore inhibit tumor growth and progression of breast cancer, depending on the regulation of the 14-3-3 sigma/MDM2 axis." (PMID 35890172, 2022). "Similarly, MDM2 overexpression antagonized the apoptosis-promoting effect of 14-3-3 sigma overexpression in the transfected breast cancer cells." (PMID 35890172, 2022). "The result showed that ZLM-7 treatment could alter the expression of 14-3-3 sigma and MDM2 by upregulating the expression of 14-3-3 sigma, and interestingly, downregulating MDM2 expression in breast cancer cells." (PMID 35890172, 2022). "Previously, MDM2 amplification has been reported to relate to estrogen receptor status and its presence has been indicated in human breast cancer cell; was observed to be manipulated with diosgenin in the third cluster of the PPI binding (binding energy −8.5 kcal/mol)." (PMID 36686654, 2022). "Molecular mechanistic understanding has revealed that IGFBP1 is a key component of G protein-coupled estrogen receptor 1 (encoded by GPER1) which regulated the sensitivity of breast cancer cells to tamoxifen, and the resistance induced by RG7388 (MDM2 inhibitor) in glioblastoma." (PMID 34737677, 2021). "We used clinical data presented in (the Cancer Genome Atlas Program) TCGA to extend this research and investigate if a correlation between overexpression of MDM2 gene and a decrease in patient survival is found in any of the molecular subtypes of breast cancer." (PMID 34572735, 2021). "Genetic variations (for example, SNPs) in the MDM2 and MDM4 genes may also be associated with breast cancer." (PMID 33669778, 2021). "In breast cancer we identified rearrangement hot spots near CCND1 and in glioma near CDK4 and MDM2 and could directly associate this with increased expression." (PMID 34891161, 2021). "Accordingly, high levels of MDM2 are detected in ERα+ breast carcinoma." (PMID 34307167, 2021). "The molecular mechanism of chemoresistance acquisition resulting from high expression of MDM2, which we proposed here, might contribute to the poor prognosis for breast cancer (this article) and non-small cell lung cancer patients with high expression of MDM2." (PMID 34572735, 2021). "A decreasing endogenous MDM2 level (using specific siRNA) in different breast cancer cell lines led to the same conclusions: only in the case of SKBR3 cells (which represent the HER2 subtype of breast cancer) did downregulation of MDM2 gene result in the decrease in cell survival." (PMID 34572735, 2021). "It has also been reported that the mdm4/mdm2 heterodimers are upregulated not only in the brain and nerve tumor tissues, breast cancer, soft tissue sarcomas, type 1 diabetes, and systemic lupus erythematosus, but also in the parathyroid glands of patients with renal secondary hyperparathyroidism." (PMID 35070964, 2021). "Interestingly, MDM2 overexpression was found to induce chemoresistance and additionally enhances invasiveness and motility of breast cancer cells." (PMID 33663585, 2021). "In human breast cancer, the MDM2 protein level was identified as a prognostic biomarker." (PMID 34572735, 2021).
breast carcinoma (continued). "MDM2/MDMX proteins are frequently elevated in hormone receptor-positive (ER+) breast cancer." (PMID 33663585, 2021). "Our results revealed that some SNPs of MDM2 and MDM4 might be significantly associated with the breast cancer characteristics." (PMID 33669778, 2021). "Intriguingly, ER+ breast cancers are more likely to have higher levels of MDM2." (PMID 34830174, 2021). "The overall positive effects of estrogenic hormones on MDM2, at the mRNA and protein levels, suggest that anti-estrogenic therapies in breast cancer could synergize with MDM2-targeted drugs." (PMID 34307167, 2021). "siRNA-mediated ablation of ERα or treating ER+ breast cancer cells with tamoxifen (an ERα modulator) or fulvestrant – (a pure ERα antagonist that also leads to ERα degradation) blocks the E2-dependent upregulation of MDM2." (PMID 34804982, 2021). "We have to admit that this is the first analysis of polymorphisms in the MDM2 and MDM4 genes in relation to the breast cancer clinical characteristics in Lithuania; consequently, a much larger cohort of breast cancer patients would be required to verify our findings." (PMID 33669778, 2021). "The follow-up studies of breast cancer patients that could be used to monitor their survival would help to elucidate the mechanisms and patient outcomes related to MDM2/MDMX inhibition." (PMID 31892970, 2020). "Furthermore, a previous study revealed that CDK4 and MDM2 mutations occurred in melanomas and liposarcoma, while ERBB2 mutations occurred in breast cancer, EGFR mutations occurred in astrocytoma, and MYCN mutations occurred in neuroblastoma." (PMID 32711494, 2020). "Breast cancer patients could therefore be treated with both MDM2/MDMX inhibitors and PD-1/PD-L1 inhibitors to achieve an optimal therapeutic effect." (PMID 31892970, 2020). "It has been shown in breast cancer cells that BCL11A positively regulates MDM2 expression." (PMID 32266150, 2020). "In the dose expansion (n = 68), patients with MDM2-amplified (well-differentiated and de-differentiated liposarcomas [WDLPS and DDLPS], glioblastoma multiforme [GBM], or other solid tumors [OST]), MDM2-overexpressing ER+ breast cancer (BC), or MM received AMG 232 at the maximum tolerated dose (MTD)." (PMID 31359240, 2020). "USP15 stabilizes MDM2, a well-known cancer gene, to regulate cancer-cell survival and mediates antitumor T cell responses, while increased expression of MAD1L1 is associated with poor prognosis in breast cancer." (PMID 31024613, 2019). "We also documented that MDM2 promotes tumorigenesis of ERα+ breast cancers." (PMID 30642351, 2019). "However, the observed trends towards an increased breast cancer risk and a poor survival are at odds with the proposed molecular function of the SNP285C-allele to reduce binding of SP1 and expression of MDM2." (PMID 30691044, 2019).
breast carcinoma (continued). "Intriguingly, we observed a statistically significant inverse correlation between MDM2 and HBP1 protein levels in human uterine cervix cancer, thyroid cancer, and breast cancer with high expression of MDM2 (compared with carcinoma versus para-carcinoma) using immunohistochemistry assay." (PMID 30816344, 2019). "High levels of MDM2 have been detected in 38% of human breast cancer cases." (PMID 30956778, 2019). "MDMX and MDM2 are expressed in multiple subtypes of breast cancer." (PMID 30642351, 2019). "Many human breast cancers overexpress the E3 ubiquitin ligase MDM2 and its homolog MDMX." (PMID 30642351, 2019). "Thus, small-molecule MDM2 antagonists can indirectly reduce the aggressive phenotype of breast cancer cells by suppressing the SASP of neighboring cells, suggesting an unexpected potential therapeutic benefit." (PMID 29402901, 2018). "In the present study, we examined the MDM2 splice variants MDM2-A, -B and -C for their biological functions in breast cancer cells with and without chemotherapy treatment." (PMID 28415963, 2017). "The MDM2 isoforms could be expressed in normal tissues, as well as, in human cancers such as pediatric rhabdomyosarcoma, breast cancer, glioblastoma, and liposarcoma." (PMID 29065514, 2017). "Importantly, estrogen-receptor positive (ER+) breast cancers overexpress MDM2 and estrogen mediates this expression." (PMID 28615518, 2017). "The location of these MDM2 isoforms depends on the cell type and its environment as seen in the case of MDM2-B which can be found exclusively in the cytoplasm of breast cancer cells and lung carcinomas, but is located in the nucleus of mouse embryonic fibroblasts." (PMID 29065514, 2017). "We observed that MDM2 expression was required for the lack of luminal clearance that associates with breast cancer cell growth in matrigel and that knockdown of MDM2 resulted in luminal clearance." (PMID 28615518, 2017). "MDM2 is negatively regulated by specific microRNAs such as miR-1827 and miR-340, and overexpression via multiple mechanisms is observed in various types of human malignancies, including sarcomas, gliomas, hematological malignancies, and breast cancer." (PMID 27659536, 2016). "This study also validates the effectiveness of dually targeting NFAT1 and MDM2 in breast cancer." (PMID 27105525, 2016). "To develop in vitro models to examine the mechanism of MDM2's function in breast cancer biology, we determined the protein expression of MDM2 in three human breast cancer cell lines (MCF-7, MDA-MB-231 and MDA-MB-435) and one human mammary epithelial cell (HBL-100) by western blotting." (PMID 27184007, 2016). "We used the luminal human breast adenocarcinoma cell lines ZR-75-1 and MCF7 as in vitro model systems of ERα-positive breast cancer, and we investigated how loss of ERα expression affected MDM4 gene expression at the protein and mRNA levels, as compared to its effects on MDM2 gene expression." (PMID 26909605, 2016).
breast carcinoma (continued). "Based on our observations from ChIP datamining studies, we postulate that ERα-dependent overexpression of MDM4 and MDM2 in human breast cancer is mediated, at least in part, by the ability of ERα to directly bind to and transcriptionally upregulate the MDM4 and MDM2 genes." (PMID 26909605, 2016). "Finally, we found that MDM2 expression correlated with EMT markers and Snail: Snail expression was inversely associated with E-cadherin in human breast cancer samples." (PMID 27184007, 2016). "Furthermore, the levels of p21WAF1, MDM2, and bax decreased in spontaneous breast cancer and in the metastatic tumours of HCCR transgenic mice." (PMID 27052330, 2016). "MDM2 gene amplification occurs in diverse human malignancies, including breast cancer." (PMID 27004407, 2016). "Interestingly, MDM2 expression positively correlates with ERα expression in primary human breast tumors and human breast cancer cell lines, and ERα has been proposed to upregulate MDM2 expression." (PMID 26909605, 2016). "For instance, a higher expression of MDM2 was observed in younger women with breast cancer, whereas Adami and colleagues reported positive effects of female sex hormones on the incidence of lung cancer in women receiving hormone replacement therapy, particularly in those with a history of smoking." (PMID 27418131, 2016). "In the present meta-analysis, a significantly decreased risk was found between MDM2 SNP285 polymorphism and ovarian cancer, and a much lower OR was found for breast cancer than that for male cancers (lung and prostate cancer), which was consistent with previous studies." (PMID 27890964, 2016). "We conclude, MDM4 SNP34091 status to be associated with reduced risk of breast cancer, in particular in individuals carrying the MDM2 SNP309GG genotype, but not to be associated with either lung‐, colon‐ or prostate cancer." (PMID 26471763, 2015). "But Mdm2 amplification was found only in two samples while its overexpression was observed in 38% of all tumors in this study, which supported Mdm2 amplification occurs at a lower frequency than increased transcription or enhanced translation in breast cancers." (PMID 24667108, 2014). "MDM2 is elevated after estrogen treatment of estrogen receptor positive (ER+) breast cancer cells." (PMID 24147044, 2013).
breast carcinoma (continued). "Furthermore, mdm2 knockdown in estrogen treated breast cancer cells results in a decrease in proliferation, thus providing evidence for the importance of MDM2 in breast cancer cell growth." (PMID 24147044, 2013). "Considering that MDM2 has been indicated to correlate with cancer metastasis, we next examined whether the MDM2 inhibition by 25-OCH3-PPD has a role in breast cancer metastasis." (PMID 22911819, 2012). "We then investigated the association between the MDM2 SNP309 genotypes and breast cancer survival." (PMID 21556366, 2011). "Estrogen receptor positive breast cancers often have high levels of Mdm2." (PMID 21223569, 2011). "We observed that MCF-7 cells formed large mass-like structures in 3D and that these structures were replaced with small structures when Mdm2 was knocked down, suggesting that Mdm2 may be important for invasive behavior of breast cancer cells." (PMID 21223569, 2011). "Combination therapies involving re-activation of checkpoint pathways blocked by Mdm2 (by decreasing Mdm2 protein) may increase the efficacy of killing ERα+ breast cancers." (PMID 21223569, 2011). "However, both large cohort-based studies were unable to exclude MDM2 SNP309 involvement in breast cancer time of onset." (PMID 19144119, 2009). "A perspective study that is based on a larger sample size is necessary, and it will be important to evaluate the interaction between MDM2 SNP309 and other genetic backgrounds to identify the significance of MDM2 SNP309 on the risk and onset time of breast cancer in the Taiwanese population." (PMID 19144119, 2009). "It is unknown whether the rate of the MDM2 SNP309 GG genotype (21%) among Taiwanese breast cancer patients is significantly different from other ethnic groups." (PMID 19144119, 2009). "It is speculated that MDM2 SNP309 may play a complex role in the time of onset for breast cancer among various subgroups." (PMID 19144119, 2009).